CD163 (CD163 molecule)
Diseases named in the same sentence as CD163 in open-access papers (continued):
Sharing a sentence is not in itself a finding about the gene and the disease.
tumor (continued). "More importantly, high expression of circSMARCC1 was positively associated with colonization of CD68+/CD163+/CD206+ TAMs in tumor microenvironment." (PMID 36045408, 2022). "In particular, the CSC marker CD44 was positively associated with immune markers, such as CD163, indicating a role of M2 macrophages in tumour dedifferentiation, or CD3 and CD4, which are indicative of an immune response." (PMID 36358805, 2022). "Tumor-associated macrophages that exhibit tumor-promotive effects are M2-type macrophages, the majority of which are CD163-positive macrophages." (PMID 36497144, 2022). "Histopathological assessments suggest that the density of CD163-positive TAMs within the tumor microenvironment is associated with reduced efficacy of chemotherapy and unfavorable prognosis." (PMID 35053472, 2022). "CD68 serves as a pan-macrophage marker for tumor-associated macrophages, and CD163-labeled macrophages are mainly M2 macrophages, which promote tumor growth and metastasis." (PMID 36195882, 2022). "In breast cancer, CD163-expressing TAMs resembling an M2-like phenotype accumulated in the tumor microenvironment and were associated with poor clinical outcomes." (PMID 33763066, 2021). "The high-risk group was characterized by higher expression of CD163, which is a marker of M2-like tumor-associated macrophages (TAMs), and MYD88, which is a marker of NF-kappa-B activation, cytokine secretion, and inflammatory response." (PMID 34945004, 2021). "Further, Spi-B expression in tumor cells was significantly associated with CD163 in human TAMs, suggesting poor clinical outcomes." (PMID 34141615, 2021). "These high-risk genes were also associated with the gene expression of M2-like tumor-associated macrophages (CD163), and MYD88 expression." (PMID 34945004, 2021). "The strongest correlations were between B7H3, CD163, and Src, all of which are expressed by Kupffer cells and have been linked to tolerogenic M2 polarization of macrophages, particularly within the tumor microenvironment." (PMID 35111697, 2021). "The number of TILs (CD45+, CD3+, CD4+, CD8+, and FOXP3+) and tumor‐associated macrophages (CD163+) was counted using immunohistochemistry on tissue microarray slides." (PMID 34076969, 2021). "High infiltration rates of CD163+ cells in the PT tumor compartment were also associated with grades of differentiation (p = 0.021) and tumor stage (p = 0.030)." (PMID 34194435, 2021). "The result of the CIBERSORT algorithm revealed that GBE1 expression was significantly correlated with infiltration of CD163+ tumor-associated macrophages." (PMID 35155189, 2021). "By using CD68, a pan-macrophage marker, and CD163, an M2-like polarization macrophage marker, immunohistochemistry (IHC) was performed to identify tumor-associated macrophages (TAMs) and CLSs." (PMID 34677277, 2021). "Tumor-associated macrophages (TAMs) expressing CD163 (p = 0.0022) and Mannose (p = 0.0016) were enriched in PTLD after HCT." (PMID 33324999, 2021). "CD163 has been used as a biomarker of the anti-inflammatory M2 macrophage phenotype in tumor-associated macrophages and has been associated with tumor progression in a number of cancers including colorectal cancer (CRC)." (PMID 34367949, 2021). "We dichotomized the infiltration level of CD163+ tumor-associated macrophages into low-infiltration group and high-infiltration group based on the median value." (PMID 35155189, 2021). "CD163 can be used as an immune modulator and aids in the inflammatory response, and as a member of the tumor-associated macrophage family, it has an important impact on tumor proliferation and metastasis." (PMID 34880862, 2021). "In DLBCL, it has been shown that CREBBP/EP300 mutations are also associated with the recruitment CD68+ and CD163+ M2 macrophages to the tumor site." (PMID 35071240, 2021). "We further used TMA-based IHC to confirm the positive relationship between GBE1 expression level and CD163+ tumor-associated macrophage infiltration." (PMID 35155189, 2021).
tumor (continued). "Subgroup analysis in the hrHPV+ group (N = 43) showed that high infiltration rates of CD68+ and CD163+ cells in the PT tumor compartment were associated with lymph node (LN) metastasis (p = 0.031 and p = 0.026, respectively)." (PMID 34194435, 2021). "In conclusion, CD68+ TAM and CD163+ M2 TAM infiltration in CC were associated with tumor progression." (PMID 33928349, 2021). "In keeping with these findings, TAM from HGSC patients show a high degree of phenotypic, ontogenetic and tumour‐promoting heterogeneity, reflected, for example, by the differential expression of CD163 and cytokines associated with tumour progression." (PMID 34841720, 2021). "Secondly, a subset of CD11c+ cells was identified as macrophages, either with the CD68 pan-macrophage marker or the tumor-associated macrophage marker CD163." (PMID 33803245, 2021). "A trend of increased CD8+ cytotoxic T lymphocytes (CTLs) and decreased CD163+ tumor-associated macrophages (TAMs) and Foxp3+ regulatory T cells (Tregs) in the pCR group was revealed by IMC." (PMID 34733785, 2021). "A recent meta-analysis demonstrated that higher CD68(+) TAMs in tumor nests predicted favorable disease-free survival, and higher M2 (CD163(+)) macrophages were associated with poor survival outcomes in NPC." (PMID 34407796, 2021). "Immunohistochemical analysis of PDM model 2 using CSF1R, CD68, CD204, and CD163 revealed the presence of tumor-associated macrophage markers." (PMID 34063518, 2021). "Flow cytometric TME analysis identified (tumor associated) CD14+CD163+ and CD14+CD204+ macrophages as critical determinants for PDX propagation." (PMID 34362423, 2021). "The highest density of CD163+ tumor-associated macrophages type 2 (M2) was observed in the high-grade ChS." (PMID 33804155, 2021). "The expression level of GBE1 was associated with prognosis and CD163+ tumor-associated macrophage infiltration in LUAD, suggesting its potential utility as a prognostic biomarker and immune-related therapeutic target for LUAD patients." (PMID 35155189, 2021). "In liver metastases (LM), the intra-tumoral densities of CD163+ tumor-associated macrophages (TAM) and of total CD8+ T cells were higher than in extra-hepatic UM metastases, but the percentage of Granzyme B+ CTL was lower." (PMID 33947438, 2021). "In conclusion, the expression of GBE1 is associated with the prognosis and CD163+ tumor-associated macrophage infiltration in LUAD, suggesting that it has potential to be prognostic and immunological biomarkers in LUAD." (PMID 35155189, 2021). "The densities of CD8+ T cells, CD33+ cells (marker for myeloid‐derived suppressor cells [MDSCs]), and CD163+ cells (marker for tumor‐associated macrophages [TAMs]) in CRLM tissue were determined by immunohistochemical staining." (PMID 34464993, 2021). "Among subpopulation of macrophages, the surface marker CD163 is usually targeted to identify tumor-associated macrophages (TAMs)." (PMID 33747916, 2021). "Several studies have used CD163 as an M2 tumor-associated macrophage (TAM) marker and CD68 as a pan macrophage marker(M1+M2)." (PMID 34221962, 2021). "CD163+ TAMs are associated with poor histological grade, larger tumor size, Ki67 positivity, and LN metastasis in patients." (PMID 35237501, 2021). "We compared the number of CD163+ tumor-associated macrophages and PD-L1 expression in tumor versus stromal areas and found minimal changes in these subsets." (PMID 33594075, 2021). "It is interesting to note the CD68 expression was independently associated with poor relapse-free survival and CD163 expression was an independent prognostic factor along with tumor thickness." (PMID 34449584, 2021). "Stromal CD20+/CD68+ and CD20+/CD163+ ratios were significantly and consistently associated with T classification, tumor grade, and second primary tumors." (PMID 33494389, 2021).
tumor (continued). "We showed that a high content of CD163 + macrophages in a tumor is reliably associated with a poor prognosis, which is generally consistent with the existing concept that strong M2 tumor infiltration by macrophages is a poor prognostic sign for NSCLC." (PMID 33466316, 2021). "A high CD163+/CD68+ TAM ratio at the tumor front was associated with worse survival in a study investigating Stage I–III CRC (n = 81), whereas no such association was observed when a high CD163+/CD68+ TAM ratio was found intratumorally." (PMID 34885098, 2021). "When CD14+, CD68+ and CD163+ myeloid densities in the intratumoral tumor (IT Tumor) increased, the risk of death was found to decrease slightly but in a statistically significant manner." (PMID 34194435, 2021). "CD68- and CD163-positive tumor-associated macrophages are reported as key factors in tumor growth and metastasis through releasing chemokines such as inflammatory growth factors." (PMID 34153003, 2021). "Association of CD163+FKBP51s+ monocytes with residual tumor was also suggested by the analysis of immunophenotype in concert with MRI in four patients (two cases of complete and two of incomplete resection) that received immunophenotype after Stupp therapy." (PMID 33917598, 2021). "The result revealed that GBE1 was strongly positively related to the CD163+ tumor-associated macrophage infiltration, which was consistent with the results of CIBERSORT algorithm, TIMER database, and TCGA cohort." (PMID 35155189, 2021). "In this study, high CD3+ T-cells and CD163+ tumor-associated macrophages (TAMs) densities identify a subgroup of immune infiltrated high-grade serous carcinomas (HGSCs) with better outcomes and superior response to platinum-based therapies." (PMID 34220848, 2021). "Recent study results indicate the participation of CD163+ TAMs (M2) infiltrations in the invasive front of a tumor in EMT process, their association with mesenchymal-circulating tumor-cell (CTC) ratio, and poor prognosis in CRC patients." (PMID 33557173, 2021). "Further analysis of multivariable Cox regression showed that CD163+ macrophage infiltration at the MI and tumor size were independent high-risk factors, whereas CD68+ macrophage infiltration at the CT and H. pylori positivity had a protective effect." (PMID 34926251, 2021). "Macrophages release interferon alpha-8 (IFNA8), and we found that the high-risk group was associated with high expression of CD163, which is a marker of M2-like tumor-associated macrophages (TAMs)." (PMID 34945004, 2021). "The immunohistochemical markers CD68 and CD163 for the detection of tumor-associated macrophages are widely used." (PMID 33530441, 2021). "The tumor islet-infiltrating CD163+ tumor-associated macrophages were associated with the prognosis of nonsmall-cell lung cancer (NSCLC) patients." (PMID 35155189, 2021). "As the tumor microenvironment is an important player in tumor progression, we investigated immunohistological expression of TAM (tumor-associated macrophages) using CD163 and CD68 markers in tumors." (PMID 33747916, 2021). "We found a statin dose-dependent reduction in protumorigenic TAMs (CD68+CD163+) in both stromal (P = .021) and parenchymal (P = .003) compartments within regions of in situ tumor growth, but this association was lost in invasive regions." (PMID 32190817, 2020). "Tumor-associated macrophages (TAMs) have anti-inflammatory characteristics or are selectively activated toward the M2 phenotype, which express CD163, CD206, PD1, CD14, and CD16." (PMID 32908942, 2020). "It is characterized by a severe immunosuppressive milieu mostly triggered by suppressive CD163+ tumor-associated macrophages (TAMs)." (PMID 32899203, 2020). "The pan-macrophage marker CD68 is now generally utilized to identify tumor-associated macrophages (TAMs) in diagnostic biopsy samples, and CD163 and CD206 are used to identify M2 macrophages." (PMID 33178603, 2020).
tumor (continued). "It is known that M2-TAMs are the main tumor-associated anti-inflammatory macrophages with relatively high expression of CD163, MRC1, MS4A4, and MAF." (PMID 33303760, 2020). "Our finding of an association of CD68+/CD163+ TAMs with increased tumor cell proliferation is consistent with this protumorigenic function and argues in favor of a direct mitogenic, paracrine effect rather than a reduction in immune-mediated cytotoxicity." (PMID 32190817, 2020). "A combination of fatty breasts (VLD), abundance of M2-like TAMs (CD163+) and tumor HA associated with poor survival, as survival was 88–89% in the absence of these factors but only 40–47% when all three factors were present (p < 0.001)." (PMID 31720917, 2020). "Next, we plotted the expression of the general macrophage marker CD68 and the tumor-associated macrophage marker CD163 versus F2R in tumor-only datasets." (PMID 32809114, 2020). "The expression of CD163, a highly specific marker of M2 macrophages, is associated with tumor proliferation, metastasis, and prognosis." (PMID 32485960, 2020). "Compared to anti-CSF-1R blocking antibody causing general TAM depletion, specific depletion of CD163+ TAMs was shown to be a more efficient inhibitor of tumor growth." (PMID 32752088, 2020). "Immune cell infiltrates determine prognosis, and high CD4/CD3 ratio and high counts of CD163 positive tumor-associated macrophages determine prognosis." (PMID 32658932, 2020). "Recent studies reported that CD163+ macrophages were associated with PD-L1 expression on tumor cells in several human cancers." (PMID 32630659, 2020). "In the present material of 262 breast cancer patients, we explored the combined impacts on survival of fatty breasts (VLD), M2-like (CD163+) TAMs and tumor HA, and their possible associations with T2D." (PMID 31720917, 2020). "Our previous morphological analyses demonstrated that the main reactive cells within mUM are CD163+ tumour-associated macrophages (TAMs), i.e., protumourigenic M2 phenotype." (PMID 33008022, 2020). "Consistently, a number of in vitro studies showed that NLCs are functionally equivalent to tumor-associated macrophages (TAMs) described in solid tumors, and express CD163, CD206, CD14 and CD68 on the cell surface." (PMID 32155826, 2020). "Lo Russo revealed that M2-like CD163+ CD33+ PD-L1+ tumor-associated macrophages can block anti-PD-1 antibody functional activity by interacting with the Fc domain of the antibody." (PMID 32727409, 2020). "qRT-PCR analysis of tumor samples from renal cell carcinoma patients revealed positive correlation between M2-associated genes (CD163, FN1 and IRF4) and reduced survival." (PMID 32486098, 2020). "With regard to macrophage polarity, increasing statin dosage showed a statistically significant association with diminished CD68+/CD163+ staining in parenchymal and stromal areas within in situ tumor regions." (PMID 32190817, 2020). "Scoring of macrophages in different geographical regions by manual and automated (using Visiopharm software) methodologies revealed a significant association between MUC1-ST and CD163 on the edge of the tumour nests." (PMID 33149188, 2020). "These IL-23-producing cells and IL-17 producing cells were, at least in part, CD163 + tumor-associated macrophages (TAMs) and CD4 + IL-17 + Th17 cells, respectively." (PMID 33178182, 2020). "Tumor-associated macrophages (TAMs) have been reported to express high levels of CD163 (i.e., M2 phenotype) and the density of these TAMs is associated with unfavorable clinical outcome in numerous human cancers." (PMID 32824692, 2020). "Stromal CD163+ infiltration was significantly associated with the tumor location, and higher in the tongue (p = 0.02)." (PMID 32630659, 2020). "M2-like macrophages are in general major producers of IL-10, which was also supported by our data showing a strong correlation between IL-10 and the tumor-associated macrophage marker CD163 in both patient cohorts." (PMID 30879106, 2019).
tumor (continued). "In this study, we found that increased CD163+ TAMs infiltration in the tumor invasive front was significantly associated with EMT, MCTC ratio and dismal prognosis in CRC." (PMID 30927925, 2019). "The dominant leukocyte population in pre-infusion and post-infusion biopsies is CD163+ tumor-associated macrophages (TAM)." (PMID 31651363, 2019). "By contrast, either CD163 or CD68 expression at tumor stroma was insignificantly associated with MCTC ratio." (PMID 30927925, 2019). "HLA-DR+ (M1-like) macrophages have an anti-tumoural effect, whereas CD163+ (M2-like) macrophages are associated with tumour initiation, progression, invasion and angiogenesis." (PMID 31703742, 2019). "Recent studies have shown that CD163-positive macrophages are associated with histological grade and poor prognosis of tumours." (PMID 31186031, 2019). "High level of infiltration of stromal CD163+ macrophages was associated with higher histologic grade, higher Ki-67 proliferation index, and higher tumour volume." (PMID 30816272, 2019). "The CD68+CD163+CD206+ macrophages (12%) were the least associated with tumor cells within this range." (PMID 31477692, 2019). "Prior to infusion, the TME exhibited minimal leukocyte infiltration; CD163+ tumor-associated macrophages (TAMs) were the dominant population." (PMID 31651363, 2019). "A high count of tumour-infiltrating CD163+ M2 macrophages was significantly associated with decreased overall survival in pooled meta-analysis." (PMID 30808992, 2019). "NHG3 tumors showed a significantly higher proportion of CD163-expressing tumor cells, suggesting an association between macrophage phenotype and poor differentiation." (PMID 30915533, 2019). "In contrast to CD163, a high count of tumour-infiltrating CD57+ NK cells was significantly associated with improved overall survival in pooled meta-analysis." (PMID 30808992, 2019). "In the HPV− cohort (n = 158), LNM were associated with diffuse PD-L1 tumor-cell expression, high intratumoral CD163+ macrophage infiltration, and low number of stromal CD8+ T-cells." (PMID 29942303, 2018). "These tumors differ in their content of CD163+ tumor associated macrophage (TAM) that resemble M2 monocytes." (PMID 30400835, 2018). "In the HPV− cohort (n = 158), LNM were associated with diffuse PD-L1 tumor-cell expression, high intratumoral CD163+ macrophage infiltration and low number of stromal CD8+ T-cells, while only the first two parameters were associated with DSS." (PMID 29942303, 2018). "CD163, which marks tumor associated microglia/macrophages (TAMs), showed the highest expression level in GBM patients." (PMID 30375429, 2018). "On the basis of the expression of polarization markers, TAMs in human GC was verified as pro-tumor phenotype, characterized by increased M2-associated markers (CD163, CD206)." (PMID 29567987, 2018). "In vitro assays revealed that agalactosylated IgG upregulated tumor-associated macrophage markers CD163 and CD204 in human U-937 cells and peripheral macrophages." (PMID 30469416, 2018). "The data indicates that there is a closer association between the loss of tumor vascular integrity than IDH1 mutational status in the appearance of CD163+ TAM." (PMID 30400835, 2018). "High expression of CD163 is a potential indicator to evaluate the status of tumor associated macrophages (TAMs), regulatory T cells (Tregs), myeloid-derived suppressor cells (MDSCs) and cancer associated fibroblasts (Cafs)." (PMID 29152078, 2017). "Immunosuppressive cell populations analyzed included Foxp3+ regulatory T cells (Treg cells) and CD163+ tumor-associated macrophages (TAMs), shown to play a crucial role in various cancer types." (PMID 29190964, 2017). "CD163 is a scavenger receptor upregulated by tumor-associated M2 macrophages in an anti-inflammatory tumor microenvironment." (PMID 28428887, 2017). "FTH1 also serves as a novel marker for macrophages, and FTL is a prognostic marker in tumor-associated macrophages, along with CD163." (PMID 28957348, 2017).